ARAP2 (ArfGAP with RhoGAP domain, ankyrin repeat and PH domain 2)
Description:
Phosphatidylinositol 3,4,5-trisphosphate-dependent GTPase-activating protein that modulates actin cytoskeleton remodeling by regulating ARF and RHO family members. Is activated by phosphatidylinositol 3,4,5-trisphosphate (PtdIns(3,4,5)P3) binding. Can be activated by phosphatidylinositol 3,4-bisphosphate (PtdIns(3,4,5)P2) binding, albeit with lower efficiency (By similarity).
Synonyms: CENTD1; PARX
Tractability: PROTAC: ubiquitination databases record sites on it; its protein half-life has been measured.
Gene: Protein-coding gene on chromosome 4 (35,948,221 to 36,244,777, reverse strand). Ensembl gene ENSG00000047365.
Subcellular location: Cytoplasm
Subcellular location (Human Protein Atlas): Focal adhesion sites; Actin filaments
Pathways (Reactome):
Signal Transduction: CDC42 GTPase cycle; RAC1 GTPase cycle; RAC3 GTPase cycle; RHOA GTPase cycle
Gene Ontology:
Molecular function: phosphatidylinositol-3,4,5-trisphosphate binding; GTPase activator activity
Biological process: regulation of actin cytoskeleton organization; signal transduction
Cellular component: cytoplasm
Genetic constraint (gnomAD): Loss-of-function variants: 106 observed, 140.92 expected, observed/expected ratio (o/e) 0.75, 90% interval 0.64 to 0.88. The upper end of that interval is the gene's LOEUF score, 0.88, which puts it in group 3 of 6, group 1 being the genes least tolerant of losing a copy. Missense variants: 1,722 observed, 1,646.4 expected, observed/expected ratio (o/e) 1.05, 90% interval 1 to 1.09. Synonymous variants: 568 observed, 588.63 expected, observed/expected ratio (o/e) 0.96, 90% interval 0.9 to 1.03.
Homologues: Orthologues: chimpanzee ARAP2 (99% identical), macaque ARAP2 (97% identical), dog ARAP2 (89% identical), rabbit ARAP2 (89% identical), guinea pig ARAP2 (86% identical), pig ARAP2 (86% identical), mouse Arap2 (83% identical), rat Arap2 (82% identical), tropical clawed frog arap2 (45% identical). Paralogues in human: ARAP1 (31% identical), ARAP3 (30% identical), ASAP1 (11% identical), ASAP2 (11% identical), ACAP2 (9% identical), ASAP3 (9% identical), ACAP3 (9% identical), ACAP1 (8% identical), AGAP1 (8% identical), AGAP3 (8% identical), GIT2 (7% identical), GIT1 (7% identical), and 16 more.
Diseases named in the same sentence as ARAP2 in open-access papers:
ARAP2 is named in the same sentence as 12 diseases in open-access papers, as found by Europe PMC text mining. Sharing a sentence is not in itself a finding about the gene and the disease. The quoted sentences say what the papers report.
depression (2 papers, 2022). "The top hub regulator of the yellow module, Arap2, encodes for pro-survival functions, such as Akt activity, glucose uptake, and sphingolipid metabolism, and its dysregulation leads to impaired affective behavior in animal models of depression." (PMID 34848858, 2022). "ARAP2 is associated with impaired regulation of emotions, stress, depression, and bipolar disease." (PMID 36581688, 2022).
Anxiety (1 paper, 2022). Intense feelings of nervousness, tension, or panic often arise in response to interpersonal stresses. "The intramodular network of Arap2 also included Plcβ4 and Rora, whose functional expression was associated with improvement in anxiety and depressive symptoms." (PMID 34848858, 2022).
liver fibrosis (1 paper, 2017). "Interestingly, the two patients with HBV integration in ARAP2 both had end-stage liver fibrosis and cancer recurrence." (PMID 29212479, 2017).
cancer (6 papers, 2009 to 2025). A tumor composed of atypical neoplastic, often pleomorphic cells that invade other tissues. "We found a number of genes involved in G protein-coupled receptor signaling (ARAP2, LPHN2, LPHN3, EPHA4, ADGRL2, and GPC5) consistent with observations in pan-cancer studies." (PMID 35538064, 2022). "The study also found that circ-ARAP2 influenced the endothelial–mesenchymal transition (EMT) and cancer stem cells differently by regulating miR-761/FOXM1." (PMID 35842667, 2022). "ARAP2 is a GTPase-activating protein for the ADP-ribosylation factor family, but has not been assigned specific functions in cancer." (PMID 32734521, 2020).
tumor (4 papers, 2017 to 2023). "The role of circ-ARAP2 expression on tumor progression were detected in both in vivo and in vitro." (PMID 35842667, 2022). "Results showed that circ-ARAP2 silencing suppressed tumor growth in volume and weight." (PMID 35842667, 2022). "Then a xenograft mouse model were constructed to detect circ-ARAP2 effects on tumor growth in vivo." (PMID 35842667, 2022). "Downregulation circ-ARAP2 suppressed ESCC proliferation, tumor growth and metastasis in both in vivo and in vitro." (PMID 35842667, 2022). "Tumor sphere formation assays using KYSE-150R and ECA-109R cells showed that circ-ARAP2 silencing decreased cell division." (PMID 35842667, 2022). "While its functions suggest potential roles in tumor progression and metastasis, no previous implications between ARAP2 and HBV-HCC have been reported." (PMID 29212479, 2017).
infection (1 paper, 2021). The state of being infected such as from the introduction of a foreign agent such as serum, vaccine, antigenic substance or organism. "By contrast, the SIRT2 activity-independent gene ARAP2 shows a decrease in SIRT2 enrichment during infection which is not altered by the loss of TDP-43." (PMID 34929015, 2021). "As previously demonstrated, infection causes significant recruitment of SIRT2 to the TSSs of MYLIP, ERRC5, LEF1, SYDE2 and EHHADH but not ARAP2." (PMID 34929015, 2021). "By comparison ARAP2, a SIRT2 independent gene, does not show TDP-43 recruitment upon infection." (PMID 34929015, 2021).
ARAP2 also shares sentences with these, for which no sentence is quoted: asthma (1 paper); breast carcinoma (1); epilepsy (1); Parkinson’s (1); pertussis (1); tongue cancer (1).